CD4 (CD4 molecule)
Diseases named in the same sentence as CD4 in open-access papers (continued):
Sharing a sentence is not in itself a finding about the gene and the disease.
AIDS (continued). "Our results are alsoconsistent with the SAPiT and STRIDE results, which found that cART initiation after wk improved survival or AIDS-free survival compared to initiation at8–12 wk only among individuals with severe immune suppression (i.e., CD4 cellcounts≤50 cells/μl)." (PMID 21559327, 2011). "Therefore, initiating HAART to patients with higher CD4 cell counts appears to be effective in controlling AIDS treatment-related expenses for ADEs and OIs." (PMID 21241494, 2011). "Recent clinical data suggest that production of IFNα may drive the hyper activation of the immune system resulting in CD4 T cell depletion and AIDS." (PMID 21994776, 2011). "We found that the specificity of the WHO HIV/AIDS clinical staging guidelines were at 81.1% and 86.8% at CD4 counts of 250cells/mm3 and 350cells/mm3 respectively, which was also similar to previous studies using various CD4 cell count cut-offs." (PMID 21589912, 2011). "However, controllers also often have abnormally high T cell activation levels, potentially contributing to T cell dysfunction, CD4+ T cell depletion, and non-AIDS morbidity." (PMID 21305005, 2011). "PML is an AIDS defining illness that occurs more often with a CD4 count lower than 200/mm3." (PMID 22043267, 2011). "Since R5 viruses are predominant in MTCT of HIV-1, the interaction of R5 viruses with CD4+CCR5+ T cells may play an important role in the pathogenesis of pediatric AIDS." (PMID 21284900, 2011). "A significantly smaller CD4+ response post-HAART occurred in those with clinical AIDS prior to HAART, a lower CD4+ nadir, a higher baseline VL, a greater number of years from HIV SC to HAART start, Hispanic ethnicity, and HAART initiation during 2000-2003 (vs. 2004-2009)." (PMID 21244701, 2011). "Our study has some limitations by the fact that it is a retrospective cohort study and the information at the time of AIDS diagnosis (particularly CD4 count and VL) may sometimes be missing." (PMID 22043301, 2011). "The mean CD4+ T lymphocyte count was 31.7 ± 38.6 cells/μl in the AIDS patients with CMV retinitis." (PMID 22115120, 2011). "In the study conducted in the state of Minas Gerais, late entry into HIV care was defined as presenting with a CD4+ T cell count <200 cells/mm3 or AIDS-defining clinical events, and the proportion of patients who received delayed antiretroviral therapy was 68.4%." (PMID 21283618, 2011). "Association of VL parameters with CD4 recovery after HAART initiation in subjects who did not develop AIDS." (PMID 21625477, 2011). "There are limited reports that, despite the loss of CD4+ve cells,CD8+ve T cells may still be functional in AIDS, although with varied avidity,less polyfunctionality and less differentiation, and targeting Env rather thanGag." (PMID 21544209, 2011). "Several studies conducted in high income countries in the past decade found that 20% to 40% of patients diagnosed with HIV were in advanced disease stages (in most studies defined as presenting with CD4 cell counts less than 200 cells/mm3 and/or a history of an AIDS-defining illness)." (PMID 21637802, 2011). "Poor CD4+ T-cell recovery upon initiation of ART is also correlated with an increased risk for both AIDS and non-AIDS diseases, emphasizing the important role of the CD4+ T-cell compartment in maintaining good health." (PMID 21298072, 2011). "It would be best to check AIDS patients with CD4+ T lymphocyte counts < 200 cells/μl." (PMID 22115120, 2011). "This CD40 signaling may be especially critical in eliciting CTL responses in conditions such as AIDS during which the number or activity of CD4+ T cells is limited." (PMID 21592361, 2011). "Furthermore, the substantial proportion of women (21% FSW, 15% VCT clients) with CD4 350–499 cells/μl who reported recent AIDS symptoms suggests potential additional treatment eligibility in this group." (PMID 21949704, 2011). "This reinforced the importance of memory CD4+ T cells in protection against AIDS progression." (PMID 21347287, 2011).
AIDS (continued). "Specifically, incrementally reducing the probability of AIDS-related mortality in patients with a history of previous opportunistic infections (attribution) by 25% for CD4 50–199/μl and 50% for CD4 ≥200/μl resulted in better estimation of the empiric survival data (Part C)." (PMID 20844741, 2010). "In AIDS patients, the number of CD4+ cells steadily decreases, and by the time opportunistic infections set in, CD4+ cells may be almost absent." (PMID 20824974, 2010). "The sensitivity analysis that excluded all patients receiving mono- or dual-antiretroviral therapy was based on 1,797 patients with a median CD4 cell count of 480 cells/μl at baseline, a median CD4 cell slope of −47 cells/μl per year, and 137 subsequent AIDS events or deaths." (PMID 20186270, 2010). "Therefore, as time on HAART extends, regular CD4 cell counts and viral load measurements should find an increasing importance in the monitoring of patients living with AIDS." (PMID 20565900, 2010). "Most had advanced AIDS, with a median CD4+ T-cell count of 64 cells/μL (IQR 23–191)." (PMID 20361038, 2010). "In addition, AVL/HIV-AIDS patients can present low CD4+ T cell counts and higher proportion of activated T lymphocytes even when HIV viral load is suppressed under HAART." (PMID 21171992, 2010). "Furthermore, five out of nine, AVL/HIV-AIDS presented low CD4+ T cell counts in spite of low or undetectable viral load." (PMID 21171992, 2010). "Another test that may be used in conjunction with a CD4+ count is the CD8+ T-Lymphocyte count, which might be able to assess the risk of rapid CD4+ cell depletion and susceptibility to developing AIDS." (PMID 22219687, 2010). "Therefore we calculated the Spearman correlation coefficients for plasmatic levels of IL-10, IL-22 and CRP and disease progression as defined by patients' viral load, CD4 cell counts, and AIDS-defining conditions." (PMID 20211031, 2010). "Case 3 had a very low CD4+ count and was the only case that met the criteria for AIDS." (PMID 21118561, 2010). "The pathological roles of Nef in the development of AIDS have been attributed to several Nef biological activities, including downregulation of the viral primary receptor CD4 and downregulation of the cell surface expression of class-I major histocompatibility complex (MHC-I)." (PMID 20659345, 2010). "Patients who started treatment earlier, with CD4 counts of between 200 and 350 cells/mm3, had significantly fewer deaths and fewer cases of TB compared with those who had deferred treatment to less than 200 cells/mm3 or when an AIDS-defining illness occurred." (PMID 20205768, 2010). "We also showed an association between the duration of HIV infection and CD4 reconstitution in addition to increased AIDS events despite a lack of evidence for these findings in a previous prospective study." (PMID 20507622, 2010). "While national guidelines in India suggest that ART be initiated if nadir CD4+ cell counts fall under 200/μL or if there is presence of AIDS-defining illness, our data only includes the CD4+ cell counts at the time of enrollment (as opposed to nadir CD4+ cell counts)." (PMID 20072610, 2010). "Furthermore, 36% of HIV-infected patients in France present to care with CD4 counts <200/μl and/or AIDS-related symptoms." (PMID 20976112, 2010). "Cryptococcal opportunistic infection is highly endemic in Cambodia (estimated prevalence in HIV-infected patients with CD4+ count ≤100 cells/μl of 20.6% (58/282) in 2004) and represents more generally a significant public health burden in South East Asian AIDS patients." (PMID 21085478, 2010). "Likewise, Nef-tg-mice showed AIDS like pathogenesis and inhibition of CD4 downregulation which has been attributed to the Nef-host protein interaction." (PMID 21179446, 2010). "Additionally, studies demonstrated improved protection from AIDS and CD4+T-cell depletion in animals immunized with a combination of antigens." (PMID 20642814, 2010).
AIDS (continued). "Also important to study are the effects of malaria on HIV prognosis: do the increases in viral load and decreases in CD4+ T lymphocytes seen during acute malaria infection have long term consequences on HIV progression to AIDS?" (PMID 19680452, 2009). "It is established that MAC is associated with shortened survival in AIDS causing a 3-fold increased risk of death irrespective of CD4 count." (PMID 20181177, 2009). "However, despite the dominance of Gag-specific CD4+ T cell responses and their correlation with lower viral loads, the vast majority of untreated chronically infected patients do progress to AIDS." (PMID 19352428, 2009). "Of significant clinical importance, our results show that, across much of parameter space, CCR5 inhibitors may force an early switch to X4 virus, greatly accelerating CD4+ T cell depletion and AIDS onset." (PMID 19680436, 2009). "A more than twofold increase of diarrhea among patients with CD4 counts less than 200 cells/μL in the present study may re-affirm the view that diarrhea to be an AIDS defining condition." (PMID 19765310, 2009). "NTS bacteremia typically presents in patients with AIDS once CD4 count falls below 200 cells/uL." (PMID 20181177, 2009). "CD4+ T cell count which represents the immune status or HIV/AIDS progression of the patients is a key factor in HIV infected persons that could affect the TB diagnosis." (PMID 19476627, 2009). "Given that HIV-1 causes CD4+ T-cell depletion and compromised immunological functions associated with AIDS, most CD4+ T-cells are not sufficient for long-term maintenance of the virus." (PMID 19486514, 2009). "During HIV-1 infection a severe depletion in CD4+ T-Cells is characteristic of the onset of AIDS." (PMID 19531207, 2009). "As expected, CD4+ T-cell count at AIDS diagnosis was a strong determinant of survival." (PMID 19214229, 2009). "As an experimental AIDS vaccine approach designed to uncouple immune activation from ongoing virus replication and turnover of CD4+ lymphocytes, we and others have developed genetic systems for producing strains of SIV that are limited to a single cycle of infection." (PMID 19165322, 2009). "As know, toxoplasma infection may speed up the AIDS-related disease progression, particularly in those with their CD4+ T-cell counts below 200 cells/μL." (PMID 19098990, 2008). "Notably, it has been shown previously that decreases in the absolute numbers of CD8+CD28+ T cells are predictive for progression to AIDS in HIV-1 infected individuals and associated with declining CD4+ T cell counts in SIV-infected SMs." (PMID 18636106, 2008). "Importantly, significant less percentage of individuals in HIV/HCV coinfected group progressed into AIDS stage defined as CD4+ T-cell counts <200 cells/μl during our observation." (PMID 19098990, 2008). "In earlier studies when no therapy or only zidovudine monotherapy was used, CD4 < 15% significantly increased the risk of AIDS and death." (PMID 18957095, 2008). "Hence, some studies have shown that genetic diversity and divergence from the infecting strain increase during HIV-1 infection but become stable or even decrease in the advanced stage of disease, with the lower CD4+ T cell counts and progression to AIDS." (PMID 18778482, 2008). "At this time patients who were HIV infected and had a CD4 count <350 were considered to have AIDS." (PMID 18781195, 2008). "Remarkably, the CART approach also showed that the CCL3L1-CCR5 GRGs assist in AIDS prognosis mainly during early-stage disease, such as when baseline CD4 cell counts are greater than 453 cells/mm3, a CD4 cell count threshold that is well above the point at which ART is currently recommended." (PMID 18776933, 2008). "Despite continuing advances in our understanding of AIDS pathogenesis, the mechanism of CD4+ T cell depletion in HIV-1-infected individuals remains unclear." (PMID 18445273, 2008).
AIDS (continued). "HIV-infected partners with a CD4 count between 350–550 cells/mm3 are randomly assigned to initiate ART at enrollment or to delay ART until their CD4 T-cell count falls below 250 cells/mm3 or they develop an AIDS-defining illness." (PMID 19014659, 2008). "In the ACS on HIV-1 infected drug users, we could also not demonstrate an association between polymorphisms in the regulatory region of the CypA gene and survival to CD4+ T-cell counts below 200 cells per μl or AIDS according to the 1987 and 1993 definitions." (PMID 19092998, 2008). "Finally, we conclude that inhibiting the CD4 downregulation function is the most promising Nef-targeted approach for developing a new anti-viral as a contribution to combating AIDS." (PMID 18808677, 2008). "The advent of HAART has led to a dramatic decline in AIDS-related morbidity and mortality by decreasing plasma viremia and increasing CD4+ T cell counts, normalizing the progenitor cell function and restoring CD4+T-cell functions." (PMID 18315888, 2008). "However, the post-test probabilities of developing AIDS differed according to a person's GRG or CD4 cell count." (PMID 18776933, 2008). "The associations between type of diarrhoea, parasites isolated and CD4 counts of 366 AIDS patients." (PMID 18713475, 2008). "This may reflect the limitation in self reporting of CD4 counts and/or AIDS diagnosis because the data fail to reflect how ill the patients are." (PMID 19102765, 2008). "In the Prospective Evaluation of Cardiac Involvement in AIDS (PRECIA) study, before the introduction of HAART, the incidence of pericardial effusion was 11% per year, and it was associated with shorter survival and lower CD4 counts." (PMID 19936197, 2008). "Patients in this study had relatively advanced HIV/AIDS, with a median CD4 cell count of 108 at study entry; costs may differ in other settings where patients initiate care with less advanced disease." (PMID 18275615, 2008). "Some of these subjects may have been incorrectly classified and may not have needed antiretroviral therapy, while others may have had AIDS defining conditions despite a high CD4 count." (PMID 18307778, 2008). "Selection of CD4-independent variants has also previously been shown to occur in macaques with rapid progression of simian AIDS and was characterized by absent or transient humoral and cellular immune responses." (PMID 17645788, 2007). "Since HIV infected individuals with low CD4 T-cell count or high viral load have a higher probability to die of AIDS, slow progressors are overrepresented later after infection, such that curves are biased upwards for CD4 T-cell count and biased downwards for viral load." (PMID 17888148, 2007). "However, HIV RNA level and CD4 T-cell count showed qualitatively similar evolution over time after seroconversion, also when stratified by rate of progression to AIDS." (PMID 17888148, 2007). "One important limitation of this study is that external factors, such as health worker trainings, human resource shifts and the influx of AIDS drugs, particularly in the post-intervention period, likely impeded the study's ability to detect a significant impact of the CD4 nurse intervention." (PMID 17328804, 2007). "Hence, CD4 T-cell count and HIV RNA level show similar trends from 4 to 1.5 years before AIDS diagnosis, but during the last 1.5 years CD4 T-cell count changes more rapidly." (PMID 17888148, 2007). "Since the effects of cube root of CD4 T-cell count and base-10 logarithm of viral load on AIDS risk showed almost no deviations from linearity, this scale is used in the graphs." (PMID 17888148, 2007). "Treatment criteria included a CD4 cell count <200 cells/μl or an AIDS-defining illness." (PMID 17555564, 2007). "In addition, the objective of HAART therapy is to increase CD4 count, and thus reduce the onset of AIDS-defining illnesses and other disease which require inpatient care." (PMID 17022826, 2006).
AIDS (continued). "The mutant viruses keep continually damaging or killing the cells of the immune system (mainly CD4+ lymphocytes) and, thus progressively destroy the body's ability to fight opportunistic infections and certain cancers resulting in AIDS and finally death in 7 to 10 years." (PMID 16939652, 2006). "We conclude that the CD4 percentage may be used instead of the CD4 count to predict the time to an AIDS-related event." (PMID 16916461, 2006). "At pre PI-ART, the mean age of the 72 patients was 41 (SD 9, range 23 – 65) years, 59 were of Swedish origin, 61 had prior antiretroviral treatment with only nucleoside analogue reverse transcriptase inhibitors, 32 had a CD4 count of <200 × 106 cells l-1 and 28 had an AIDS diagnosis." (PMID 15871738, 2005). "We evaluated long-term HIV viral load (VL) responses to HAART as a risk factor for AIDS events (AE) that is independent of CD4 responses." (PMID 16262894, 2005). "Additionally, S.K. Barta’s team integrated CD4+ T-cell counts, viral load, and AIDS history into a HAL-specific prognostic model, which outperformed the traditional aaIPI for OS prediction and risk stratification, although its performance for predicting CR and PFS remained limited." (PMID 40723865, 2025). "Although not all deaths at low CD4 counts are AIDS‐related, a CD4 count below 200 might be a valid proxy for AIDS‐related mortality due to extremely strong associations between low CD4 and AIDS‐related mortality." (PMID 40826829, 2025). "The induction of apoptosis in CD4+ T cells, whether directly by viral proteins like Vpr, Tat, and Nef, or indirectly through bystander effects and inflammatory responses, serves as a major contributor to immune dysfunction and AIDS progression." (PMID 40072080, 2025). "One of the earliest examples was the acceptance of RCT evidence showing increases in CD4 counts (surrogate endpoint) for improvements in overall survival resulting in approval of the first wave of antiviral drug treatments for acquired immunodeficiency syndrome (AIDS)." (PMID 40932851, 2025). "Fifth, in our prespecified primary hierarchical models we did not adjust for clinical severity indicators (HIV disease stage, CD4+ T-lymphocyte count categories, AIDS-related symptoms) to avoid potential over-adjustment; however, this choice may allow residual confounding." (PMID 41415224, 2025). "This phase is characterized by a progressive decrease in CD4+ T lymphocyte levels and an increase in viral load in the bloodstream and lymphoid organs, triggering several alterations in the immune system and consequently the occurrence of opportunistic infections characteristic of AIDS." (PMID 40367013, 2025). "Individuals with well-controlled HIV, who have undetectable viral loads and CD4 + counts above 500 cells/mm3, may experience a less severe course of mpox compared to those with advanced HIV or AIDS, who are at higher risk for severe disease due to significant immunosuppression." (PMID 40561075, 2025). "Furthermore, AIDS-defined disease and CD4 < 200 cells/μL occur in PLWH with advanced AIDS, and the individuals may develop LLV due to complications or improper medication." (PMID 39727007, 2025). "The immediate initiation group started treatment when their CD4 + count exceeded 500 cells/ μ L, while the delayed start group deferred treatment initiation until their CD4 + count had fallen to 350 cells/ μ L or at any point where the study participant developed AIDS." (PMID 40339051, 2025). "Also, γ-secretase complex inhibition, a key player of Notch signaling, decreases IL-17, IFN-γ, and CD4+ T cell differentiation into Th17 cells, inflammatory mediators of CD4+ T cells, suggesting a role as a therapeutic strategy particularly in the context of AIDs affecting the intestine." (PMID 40299348, 2025). "The virtual absence of CD4 T cells in some AIDS patients or the loss of B cells in patients on rituximab may, therefore, impact the test." (PMID 39086476, 2024).